NLRP3 (NLR family pyrin domain containing 3)
Diseases named in the same sentence as NLRP3 in open-access papers (continued):
Sharing a sentence is not in itself a finding about the gene and the disease.
depression (continued). "Genetic knockdown of thalamic HIF-1α and NLRP3 significantly attenuated mechanical allodynia and anxiety- and depression-like behaviors following thalamic hemorrhage." (PMID 36944982, 2023). "The results of in vitro were consistent with in vivo experiments, which further confirmed the role of NLRP3 inflammasome in cognitive decline in depression." (PMID 37165444, 2023). "We found that thalamic hemorrhagic stroke causes mechanical allodynia, anxiety- and depression-like behaviors, and peri-thalamic lesion site HIF-1α/NLRP3 signaling upregulation and glial cell activation." (PMID 36944982, 2023). "In various animal models of stress-induced depression, activation of NLRP3 signaling positively correlates with depressive-like behavior." (PMID 37296642, 2023). "In this study, we used a mouse model of depression generated by LPS and discovered that LPS activated the NLRP3 inflammasome in the hippocampal region." (PMID 36909194, 2023). "It was aimed to explore the efficacy of luteolin in a mouse model of dry eye comorbid depression and its molecular mechanism via Sirt1/NF-κB/NLRP3 signaling pathway." (PMID 36641776, 2023). "It therefore indicates that the suppression of hippocampal NLRP3 inflammasome activation contributes to the H2S prevention of LPS-induced depression-like behavior." (PMID 37626978, 2023). "This study is the first clinical study investigating the possible role of the NLRP3 inflammasome in comorbid AMI with depression." (PMID 37763063, 2023). "The increase in NLRP3 levels and the increased likelihood of depression in patients with myocardial infarction can be considered as an important starting point for a possible common nexus between AMI and depression." (PMID 37763063, 2023). "The most striking finding of this study is that inhibiting thalamic HIF-1α/NLRP3 inflammatory signaling was effective to prevent the anxiety and depression related to CPSP." (PMID 36944982, 2023). "The NLRP3/IL-1β pathway of microglia in the ACC of AR mice is involved in the pathological process of anxiety and depression-like behavior, and the loss of TET2 further activates the NLRP3/IL-1β pathway of microglia in AR mice." (PMID 38012545, 2023). "At the same time, phenolic metabolites represented by Malvidin have beneficial effects on anxiety and depression by targeting and regulating NLRP3, NLRC4 and AIM2 inflammasomes." (PMID 37474898, 2023). "The neurocircuit mechanisms through which thalamic HIF-1α/NLRP3 inflammatory signaling causes CPSP-related anxiety and depression are unclear." (PMID 36944982, 2023). "In an animal study, clomipramine was shown to attenuate lipopolysaccharide (LPS)-induced depression in a mouse model by partially modulating NLRP3 inflammatory vesicles." (PMID 37492068, 2023). "The main aim of this study was to investigate the possible role of the NLRP3 inflammasome and hsCRP, which are thought to play a role in depression and AMI comorbidity." (PMID 37763063, 2023). "For instance, the previous report depicted the role of the NLRP3 inflammasome in LPS-induced depression." (PMID 36909194, 2023). "Existing evidence shows the anti-depression role of MOOs on the basis of NLRP3-mediated inflammation, cerebral 5-HT production, and microbiota-associated energy metabolism." (PMID 36765376, 2023). "Subsequently, we analyzed how the inhibition of acupuncture on the activation of NLRP3 inflammasome alleviates depression." (PMID 36925735, 2023). "Research of depression has demonstrated that NLRP3 is involved in the A1 differentiation of RAs,21 and such effect is associated with the activation of downstream NF‐κB signaling." (PMID 37269079, 2023). "NF-κB functions not only as an activation signal for the NLRP3 inflammasome but also as a transcription factor that regulates NLRP3 expression, thereby jointly mediating the occurrence and development of depression." (PMID 37954847, 2023).
depression (continued). "The results of this study indicate that inflammation factors, such as ROS and NLRP3, play an important role in depression." (PMID 37629568, 2023). "We used CUMS model of depression and added probiotic administration as a comparison to explore the role of microbiota on NLRP3 inflammasome." (PMID 37293210, 2023). "Recent studies on the relationship between depression and systemic comorbid diseases focused on the possible role of the nucleotide-binding oligomerization domain (NOD)-like receptor protein 3 (NLRP3) inflammasome underlying their pathophysiology." (PMID 37763063, 2023). "Increasing researches demonstrated that NLRP3 activation was the key factor in the pathogenesis of depression." (PMID 37293210, 2023). "Collectively, the present study highlights new findings on the important role of NLRP3 inflammasome in the development of cognitive decline in depression." (PMID 37165444, 2023). "The microglia-specific ablation of NLRP3 was recently shown to markedly reduce A1-like astrocyte induction and lead to the alleviation of neuronal alteration both in vitro and in vivo depression-like mice models." (PMID 36675113, 2023). "Since there are few studies involving acupuncture to regulate NLRP3 inflammasome in the treatment of other CNS diseases, our study only discusses five diseases, including AD, VD, depression, stroke, and SCI." (PMID 36925735, 2023). "Evidence has suggested that the P2X7 receptor (P2X7R), NLRP3, and IL-1β play an important role in depressive disorder." (PMID 36979246, 2023). "AAV-transfected mice did not exhibit depressive-like behavior or hippocampal neuronal damage after ethanol exposure, confirming that NLRP3 is critical for ethanol-induced depressive disorder." (PMID 36280756, 2023). "Recent studies have shown the activation of P2X4-mediated NLRP3 inflammasome signaling in multiple models, including the hippocampus of rats with comorbidities of chronic pain and depression." (PMID 35153623, 2022). "Production of reactive oxygen species (ROS) and activation of the calpain system and the NOD-like receptor protein 3 (NLRP3) inflammasome are closely related to the pathogenesis of depression." (PMID 35498131, 2022). "Recent studies have shown that NLRP3-regulated pyroptosis is involved in various neurodegenerative and metabolic disorders, such as Parkinson’s disease and diabetes as well as depression." (PMID 35496273, 2022). "Catalpol ameliorates depression-like behavior in CUMS mice through oxidative stress-mediated NLRP3 inflammasome and neuroinflammation." (PMID 36353492, 2022). "It has been reported that isoliquiritigenin can suppress NLRP3-mediated pyrophosphorylation to improve depression." (PMID 36267291, 2022). "In summary, our experiment demonstrated that PAP ameliorated CUMS-induced depression via AMPK/Sirt1/NF-κB/NLRP3-mediated pyroptosis." (PMID 35401226, 2022). "NLRP3 inflammasome activation drives the progression of depression and is detrimental to post-stress recovery." (PMID 35722622, 2022). "For example, fluoxetine affects depression by inhibiting the activation of NLRP3 inflammasome in microglia." (PMID 35810159, 2022). "Catalpol, phosphodiesterase-4 inhibitors, and Kai Xin San have been demonstrated to improve CUMS-induced depression-like behavior in mice through NLRP3 activation." (PMID 35722622, 2022). "The study found that NLRP3 inhibitors had inhibitory effects on LPS-induced depression in a mouse model, showing the key role of the NLPR3 inflammasome in linking stress and neuroinflammatory states." (PMID 36339940, 2022). "The NLRP3 level of reactive depression was significantly lower than those of endogenous depression and healthy controls." (PMID 35295780, 2022). "The NF-κB and MAPK pathways, through their control of pro-inflammatory cytokine production and NLRP3 inflammasome activation, are recognized as two significant mechanisms in the pathogenesis of depression." (PMID 35814201, 2022).
depression (continued). "Taken together, our findings demonstrated that pyroptosis plays a crucial role in depression, and Sal ameliorates depression by suppressing the P2X7/NF-κB/NLRP3-mediated pyroptosis." (PMID 35496273, 2022). "Numerous studies have shown that activation of NLRP3 will contribute to worsening depression-like behavior." (PMID 35722622, 2022). "Recent studies have shown that stress participates in the pathology of depression by activating the NLRP3 complex, which induces pyroptosis." (PMID 35496273, 2022). "The NLRP3 inflammasome pathway, a key target in depression, mediates the production of proinflammatory cytokines such as interleukin-1beta (IL-1beta) and interleukin-18 (IL-18)." (PMID 35237160, 2022). "Isoglycyrrhizin, a flavonoid similar to quercetin, has recently been demonstrated to improve depression by inhibiting NLRP3-mediated cellular pyroptosis via the miRNA-27a/SYK/NF-κB axis." (PMID 35369029, 2022). "In animal models of depression, the depression-like phenotype is accompanied by NLRP3 inflammasome activation in the brain." (PMID 35634375, 2022). "In conclusion, NLRP3 is probably a key indicator to differentiate reactive depression from endogenous depression and healthy control." (PMID 35295780, 2022). "Reports have shown that paeoniflorin can inhibit the expression of GSDMD, caspase-11, Caspase-1, NLRP3, IL-1β, and other proteins involved in pyroptosis signal transduction in microglia, as well as reduce inflammation and relieve symptoms of depression." (PMID 36408279, 2022). "Based on the NLRP3 inflammasome, not only can we provide more potential therapeutic targets such as co-therapy for AD with anxiety and depression but also provide a reference for exploring new drugs for AD therapy." (PMID 36267291, 2022). "Acupuncture in physiotherapy can exert antidepressant effects by reducing the levels of NLRP3 inflammasome and inflammatory factors in the prefrontal cortex of depression rats." (PMID 35722622, 2022). "It has recently been reported that patients with major depressive disorder have higher levels of NLRP3, caspase-1, and IL-1β in serum or peripheral blood mononuclear cells." (PMID 36339940, 2022). "Inhibition of NLRP3 has been shown to ameliorate lipopolysaccharide- (LPS-) induced depression-like behaviors." (PMID 35498131, 2022). "The NLRP3 inflammasome has been widely recognized as an important target for mental disorders such as anxiety and depression." (PMID 36267291, 2022). "In summary, the results of this study found that the microglia, astrocytes, and NLRP3 inflammasome pathways were activated during the occurrence and development of depression, and DHC had a significant inhibitory effect on their activation." (PMID 36506556, 2022). "Current evidence has demonstrated that the NLRP3-mediated pyroptosis was a key modulator in the development of depression." (PMID 36187801, 2022). "Studies have found that rapamycin can decrease anxiety and depression in pentylenetetrazole-kindled mice by regulating the NLRP3 pathway." (PMID 36267291, 2022). "The NLRP3/ASC/caspase-1 system plays a key role in neuroinflammation in depression, and inhibition of the NLRP3/ASC/caspase-1 system reduces the expression of proinflammatory cytokines and inhibits activation of microglia." (PMID 35498131, 2022). "For instance, Baicalin exerts neuroprotective effects by inhibiting activation of the GSK3β/NF-κB/NLRP3 signaling pathway in a rat model of depression." (PMID 36452219, 2022). "In the present study we also show that Li+ inhibits activation of NLRP3 inflammasome and improves motor behaviour, cognition and depression by stimulating STAT3." (PMID 35115638, 2022). "To determine the interplay among oxidative stress, inflammation, NLRP3, and calpains in the development of depression-like behavior, we conducted this study using LPS and chronic unpredictable mild stress (CUMS) models." (PMID 35498131, 2022).
depression (continued). "Various experimental reagents can ameliorate depression-related symptoms by inhibiting the NLRP3 inflammasome." (PMID 35722622, 2022). "Studies in recent years have shown that NLRP3-dependent cellular pyroptosis is also an important mechanism of depression-related injury." (PMID 35722622, 2022). "Data from various stress-exposed animal models of depression also suggest that there is a relationship between the development of depressive-like behaviors and the NLRP3 inflammasome." (PMID 36613574, 2022). "Studies have shown that the NLRP3 inflammasome mainly exists in microglia, and the NLRP3 inflammasome plays an important role in the occurrence and development of depression." (PMID 36556951, 2022). "It was shown that dimethyl fumarate can reduce IL-1β, IL-18, caspase-1, and NLRP3 levels through the Nrf2/NF-κB signaling pathway, thus inhibiting LPS-induced microglial pyroptosis and disease manifestations in LPS-challenged depression mice." (PMID 35722622, 2022). "Studies have shown that in CUMS-induced depression, NLRP3 polarizes microglia toward the M1 phenotype." (PMID 36339940, 2022). "A previous report showed that caspase-1, NLRP3 mRNA expression, and NLRP3 protein levels are increased in mononuclear blood cells in patients with depression." (PMID 35496273, 2022). "Mechanism of electroacupuncture targeting NLRP3 inflammasome in the treatment of depression, inflammatory pain, and dry eye syndrome." (PMID 36337711, 2022). "It has also been reported that traditional Chinese medicine monomers such as resveratrol and albiflorin can help to control hippocampal inflammation through the suppression of the NLRP3 inflammasome, reducing anxiety and depression." (PMID 36267291, 2022). "Rapamycin increases catalase and superoxide dismutase and reduces NLRP3 gene expression, thereby suppressing pentylenetetrazole-induced anxiety and depression-like manifestations." (PMID 35722622, 2022). "The analytical results suggested that PAP exhibited protective effects on CUMS-induced depression possibly through the AMPK/Sirt/NF-κB/NLRP3 signaling pathway." (PMID 35401226, 2022). "Clinical data regarding the involvement of the NLRP3 inflammasome in patients with depression are scarce." (PMID 35496273, 2022). "NLRP3 inflammasome activation has even been observed in depressive patients and numerous animal models of depression." (PMID 35668399, 2022). "Reinforcing the existence of a link among inflammation, microbiota, and depression, transplantation of fecal microbiota from NLRP3 KO mice has been shown to alleviate chronic stress-induced depressive-like behaviors in recipient mice." (PMID 36613574, 2022). "The therapeutic effect of PAP on depression-like behaviors and its regulatory role on protein expressions of NF-κB, NLRP3, ASC, Caspase-1, GSDMD-N, Cleaved-IL-1β, and Cleaved-IL-18, etc., paved the way for us to understand PAP and its effect on pyroptosis." (PMID 35401226, 2022). "Studies have shown that rapamycin can decrease anxiety and depression in pentylenetetrazole-kindled mice by regulating the NLRP3 pathway." (PMID 36267291, 2022). "In summary, our present study confirmed that the CysLT2R antagonist HM3379 diminished PSD-induced neurological injury and depression-like behaviors in gerbils, which was possibly related to the suppression of the NLRP3 inflammasome/pyroptosis pathway." (PMID 35892417, 2022). "Existing evidence suggest that the NLRP3 inflammasome plays an important role in the pathological process and treatment of depression and dry eye disease." (PMID 36299901, 2022). "A novel aspect of the immune-inflammation process in the response to stress and depression: the NLRP3 inflammasome is a key molecular mechanism that translates psychological stressful stimuli into inflammatory responses." (PMID 35295780, 2022). "NLRP3 inflammasome is an inflammatory signaling molecular complex that plays a critical role in depression." (PMID 36506556, 2022).
depression (continued). "Second, the specific mechanism of NLRP3 inflammatory bodies in depression needs to be studied, which will also be discussed in the future." (PMID 36506556, 2022). "In CUMS-induced rat model of depression, icariin produces anti-neuroinflammatory and anti-depression effect partially by the inhibition of NF-ĸB pathway and the NLRP3-inflammasome/caspase-1/IL-1β axis." (PMID 35165207, 2022). "The NLRP3 inflammasome was found to be increased in the depression patient's peripheral blood mononuclear cells (PBMCs)." (PMID 35634375, 2022). "Other recent studies have described a role of hesperidin in reducing depression via corresponding mechanisms based on the NLRP3 inflammatory signaling pathway." (PMID 36499295, 2022). "Evidence also suggests that the NLRP3 inflammasome participates in stress-related depression, and depressive symptoms can be curbed with anti-inflammatory agents." (PMID 35883561, 2022). "The serum NLRP3 level of reactive depression was significantly lower than that of endogenous depression and healthy controls." (PMID 35295780, 2022). "Preclinical models of stress-induced depression, or foot-shock based stress models have utilized interfering with NLRP3 inflammasome activation using genetic knockout as well as pharmacological inhibition using several different pharmacological inhibitors." (PMID 34895246, 2021). "Moderate activation of the NLRP3 inflammasome plays a role in several diseases including Alzheimer’s disease, anxiety, and depression." (PMID 33935710, 2021). "Increased inflammation is involved in the progression of depression, and the activation of NLRP3 inflammasome in microglia is an important feature of CNS inflammation under chronic stress." (PMID 34079796, 2021). "The activation of the NLRP3 inflammasome has been observed in the mononuclear blood cells from patients with major depressive disorder." (PMID 34895246, 2021). "We also used a social defeat (SD) model to induce depression‐ and anxiety‐like behaviors and analyzed their association with endogenous BHB levels and NLRP3 activity in the prefrontal cortex." (PMID 33609086, 2021). "Several studies have demonstrated that the NLRP3 inflammasome is involved in the pathogenesis of depression and anxiety (Alcocer-Gómez and Cordero, 2014)." (PMID 33935710, 2021). "There are indications of a probable relation among NLRP3 activation, stress, and major depressive disorder." (PMID 34443594, 2021). "P2X purinoceptors 7 (P2X7) are members of the ionotropic ATP-gated receptor family, and are involved in NLRP3 inflammasome activation in different diseases like depression and diabetes." (PMID 33494430, 2021). "The caspase 1 inhibitor Ac-YVAD-CMK can inhibit the activation of NLRP3 and the inflammation induced by LPS, indicating that NLRP3 inflammasome and caspase 1 are involved in the depression model induced by LPS." (PMID 34526897, 2021). "Since the NLRP3 inflammasome signaling is a potential target of NF-κB and serves as an important role in depression, the expression and concentration of the NLRP3 cascade were detected by Western blot and ELISA separately." (PMID 33402173, 2021). "Research showed that in the LPS-induced depression murine model, following LPS treatment for 24 h, NLRP3 brain inflammation, ASC and caspase 1 and IL-1β mRNA protein levels increased significantly." (PMID 34526897, 2021). "P2X7 receptor activation by ATP followed by NLRP3 induced IL-1β release that results in neuroinflammation are major contributors of neuropsychiatric disorders, especially depression." (PMID 33889073, 2021). "The TLR4 signaling pathway and the NLRP3 inflammasome are closely related to depression and inflammatory bowel disease." (PMID 33505499, 2021). "Studies have shed light on depression treatments involving CHM constituents that suppress the overexpression or activation of NLRP3." (PMID 33466877, 2021).